PGAM5 (PGAM family member 5, mitochondrial serine/threonine protein phosphatase)
Diseases named in the same sentence as PGAM5 in open-access papers (continued):
Sharing a sentence is not in itself a finding about the gene and the disease.
tumor (continued). "Conversely, in cancer, PGAM5 is often upregulated, promoting cell survival and metabolic reprogramming under stress conditions, which might contribute to tumor progression and resistance to therapy." (PMID 41064959, 2025). "In addition, the protein expression of PGAM5 was increased in the tumours of mice in the PJA1-knockdown group than those in the control group, as determined by immunohistochemical (IHC) staining." (PMID 38906860, 2024). "Rather, most of the studies seem to suggest that PGAM5 is a promoter of tumor progression." (PMID 39063217, 2024). "Moreover, IHC staining showed that DRP1 phosphorylation was decreased in PJA1-knockdown tumours, while PGAM5 knockdown abrogated this effect." (PMID 38906860, 2024). "Inhibiting either PGAM5 or DRP1 activity rescued the tumor suppression effect induced by TIPE3." (PMID 37024453, 2023). "To validate whether TIPE3 exerted the tumor suppression effect via PGAM5, we transiently knocked down PGAM5 expressions in TIPE3 or vector overexpression HNSCC cells." (PMID 37024453, 2023). "However, when PGAM5 was knocked down, SND1-enhanced cell proliferation, tumor growth and weight of Hep3B xenografts were markedly reduced, suggesting that PGAM5 was critical for SND1-regulated cell growth in vitro and tumor growth in vivo." (PMID 35433434, 2022). "Depleting PGAM5 expression inhibited tumor growth, and restoring PGAM5 expression could enhance tumor resistance." (PMID 36189275, 2022). "Rescue of PGAM5 in S100A9‐knockout cells mostly restored tumor growth and migration in vitro and in vivo, suggesting a direct role of PGAM5 in promoting tumor progression that is responsible for S100A9‐mediated mitochondrial fission, ROS production, and EMT programs." (PMID 36041055, 2022). "These incongruous reports suggest that the functions of PGAM5 are complicated and may be specific for different tumor types or stress stimuli." (PMID 30250224, 2018). "However, PGAM5 levels were significantly higher in HCC cells than in adjacent non-tumor hepatic tissues." (PMID 30250224, 2018). "Next, we studied whether PGAM5 expression was correlated with the macrophage phenotype present in tumour tissue in NSCLC dataset GSE72194." (PMID 30526542, 2018). "Additionally, western blotting was used to compare PGAM5 expression in 7-matched pairs of cancer and adjacent non-tumor liver tissue." (PMID 30250224, 2018). "Additionally, in vivo and in vitro studies showed that depleting PGAM5 expression inhibited tumor growth and increased the 5-fluorouracil sensitivity of HCC cells." (PMID 30250224, 2018). "Furthermore, to obtain more compelling evidence, we assessed the expression levels of PGAM5 in astrocytes isolated from surgically resected brain contusion tissues from ICH patients alongside control samples obtained during deep‐seated tumor resections in non‐ICH individuals." (PMID 41201111, 2026). "However, most of the PGAM5 studies were done in tumor cell lines and therefore the physiological function of PGAM5 in vivo remains unclear." (PMID 26807733, 2016). "CASP8 and PGAM5 were identified as potential biomarkers among these, while previous studies have shown that ZBP1, TLR3, and PYGL contribute to tumor progression in KIRC." (PMID 40969770, 2025). "We detected upregulation of two pro-necrotic genes, PGAM5 and DFNA5,in tumor samples compared to normal samples." (PMID 38773214, 2024). "In tumor tissues, the staining intensity of the target genes was strong (BID, HPRT1, SMN1), high (PGAM5), or medium (FADD, KIAA1191)." (PMID 37760507, 2023). "PGAM5 regulates the phosphorylation status of Drp1 for the regulation of NKT cell-mediated immune responses in liver inflammation and anti-tumor immunity, while PGAM5 functions as a phosphohistidine phosphatase for TCR-stimulated Ca2+ influx in T cells." (PMID 37771598, 2023). "In our previous study, we found that PGAM5 regulated the phosphorylation of Drp1 in NKT cells, contributing to liver inflammation and anti-tumor immunity." (PMID 37771598, 2023).
tumor (continued). "Significantly high expression of TRAF2, PGAM5 and ATG1621 in the tumour group was an unfavourable prognostic factor." (PMID 35293027, 2022). "Of the 21 MRGs, ATG9A, PGAM5, SQSTM1, and GABARAPL1 were differentially expressed at the transcriptomic level between tumor and normal tissues." (PMID 36292980, 2022). "Immunoblotting using tumor tissue lysates confirmed the overexpression of SND1 and the knockdown of PGAM5 by shRNAs in Hep3B xenografts." (PMID 35433434, 2022). "PGAM5 and the MTS of SND1 are required for SND1-promoted mitophagy, cell proliferation, and tumor growth." (PMID 35433434, 2022). "Furthermore, expression of pro-necrotic genes, such as PGAM5 and DFNA520, were significantly upregulated in tumor samples compared to normal samples." (PMID 38773214, 2024). "To address whether PGAM5-mediated mitophagy and mitochondrial localization of SND1 are necessary for SND1 regulation of cell proliferation and tumor growth, we performed cell growth assays and xenograft experiments using Hep3B cells." (PMID 35433434, 2022). "Furthermore, ectopic expression of PGAM5 rescued the effects of S100A9 knockout and promoted tumor metastasis in vivo." (PMID 36041055, 2022). "PGAM5 dissociated from BCL-xL could control mitochondrial fission, mitophagy, and tumor cell apoptosis through FUNDC1 pathway." (PMID 36157211, 2022). "Our results are the first to clearly show that PGAM5 is frequently amplified and overexpressed in HCC tissues compared with non-tumor tissues and may be important for the acquisition of malignant HCC phenotypes." (PMID 30250224, 2018). "Furthermore, PJA1 protein expression was increased while PGAM5 protein expression was decreased in NPC tumours with nonresponse to TPF IC than those with response." (PMID 38906860, 2024). "Importantly, we demonstrate that PGAM5 and SND1-MTS are required for SND1-mediated mitophagy under FCCP and glucose deprivation treatment as well as for SND1-mediated cell proliferation and tumor growth both in vitro and in vivo." (PMID 35433434, 2022). "However, our data on PGAM5 expression has been validated by immunohistochemistry with the demonstration of PGAM5 specifically in tumour cells and not in stromal cells." (PMID 30526542, 2018). "Using immunohistochemistry, the tumour cells but not the normal tissue expressed PGAM5." (PMID 30526542, 2018). "No previous study has evaluated PGAM5 expression in HCC; thus, we detected PGAM5 protein by IHC in 178 HCC and 92 adjacent non-tumor tissues from TMUCH, and 212 HCC and 135 adjacent non-tumor tissues from SYSUCC as validation." (PMID 30250224, 2018).
cancer (19 papers, 2015 to 2025). A tumor composed of atypical neoplastic, often pleomorphic cells that invade other tissues. "In recent years, PGAM5 was associated with a newly described pathway of cell death known as oxeiptosis, which is also linked to cancer therapy." (PMID 39941813, 2025). "In cancerous tissue, only the malignant epithelial cells and associated macrophages at the periphery of the cancer expressed PGAM5." (PMID 30526542, 2018). "Therefore, one macrophage signature (‘module 36’), which is correlated with PGAM5 expression, is also associated with the outcome of the cancer patients." (PMID 30526542, 2018). "However, unexpectedly, elevated levels of PGAM5 are also associated with different types of cancer." (PMID 41064959, 2025). "Owing to its involvement in modulating mitophagy, apoptosis and necroptosis pathways, PGAM5 functions as a key player in the pathogenesis of various diseases, including neurodegenerative disorders and cancer." (PMID 41064959, 2025). "First, it remains to be determined how loss of PGAM5 interferes with FABP1 expression and how the PGAM5 and FABP1 pathways converge to impart a pro-cancer survival benefit in HCC." (PMID 37835490, 2023). "Another gene of interest, PGAM5, a mitochondrial phosphatase, demonstrated elevated expression in various cancers and a potential role in initiating necroptosis." (PMID 37760507, 2023). "Research on the mechanism of necroptosis has increased in the recent years, and PGAM5 has been found to be involved in some cancers." (PMID 36523972, 2022). "PGAM5 also regulates mitophagy through different signaling pathways, contributing to cellular senescence, neurological diseases, and cancer." (PMID 36292980, 2022). "This confirmed that both mRNA and protein expression of PGAM5 are higher in cancer tissue than in normal tissue, although it is difficult to quantify the degree of increase in protein expression." (PMID 30526542, 2018). "There was a significant correlation between PGAM5 expression in cancer tissue and the level of expression of 9 out of 49 previously-defined macrophage transcriptomic signatures with a particular one associated with patient mortality (p < 0.05)." (PMID 30526542, 2018). "Macrophages at the edge of the cancer from COPD patients showed a trend towards higher expression of PGAM5 compared to those from the other groups." (PMID 30526542, 2018). "Mitochondrial phosphoglycerate mutase/protein phosphatase (PGAM5) regulates mitochondrial homeostasis and cell death, however, little is known about its roles in cancer." (PMID 30250224, 2018). "In cancerous tissue, only the malignant epithelial cells and alveolar macrophages at the periphery of the cancer expressed PGAM5." (PMID 30526542, 2018). "In addition to its role in inflammation, PGAM5 has been intensively investigated in various diseases, including cancer and neurodegenerative disorders." (PMID 39930129, 2025). "PGAM5-mediated DRP1 activation can trigger programmed necrosis in multiple types of cancer cells." (PMID 41064959, 2025). "Moreover, the redox-sensitive nature of KEAP1 influences its interaction with PGAM5, potentially affecting the balance between cell survival and death in response to oxidative stress and cancer therapies." (PMID 39941813, 2025). "Further, PGAM5 exhibits a duality in cancer, as it functions to facilitate both the survival of the cell and tumor development by enhancing the activity of NRF2 and impeding apoptosis while participating in mitochondrial quality control processes such as mitophagy." (PMID 39941813, 2025). "In addition to PGAM1, another subfamily of PGAM enzymes, PGAM5, has also been shown to regulate several aspects of cancer cell death, including apoptosis and necrosis, by altering mitochondrial function." (PMID 37847178, 2023).
cancer (continued). "PGAM5’s inhibitory role in apoptosis through BclXL dephosphorylation and enhancement of Drp1-mediated mitophagy have been correlated to its pro-cancer survival effect, wherein PGAM5 knockdown has been shown to attenuate hepatocellular tumor growth in vitro and in xenograft models of HCC." (PMID 37835490, 2023). "PGAM5 is also expressed in alveolar macrophages at the edge of the cancer." (PMID 30526542, 2018). "Moreover, targeting the PGAM5 pathway may represent a new therapeutic strategy to improve survival outcomes of patients with HCC or other cancers." (PMID 30250224, 2018). "Our findings indicate that the expression levels of CSNK2B, MTERF3, and PGAM5 are elevated in multiple cancers, while the expression levels of PINK1 and PRKN are reduced in several cancers." (PMID 38913914, 2024). "PGAM5 activated WNT/β-catenin signaling via dephosphorylation and stabilization of β-catenin in HEK293T and cancer cells." (PMID 34630036, 2021). "The release of cleaved PGAM5 from mitochondria allows PGAM5 to interact with and dephosphorylate its candidate substrates in cytosol, such as β-catenin to activate WNT canonical signaling in cancer cells." (PMID 34630036, 2021). "There was 2.5 fold increase in PGAM5 mRNA expression in cancer tissue compared to background/ normal lung tissue." (PMID 30526542, 2018). "Toward this direction, both FUNDC1 and PGAM5 are only expressed in NSCLC epithelial cells and the adjacent macrophages which through yet unknown mechanisms sent signals to neighboring cancer cells, thus determining their fate." (PMID 30250843, 2018). "Given that PGAM5 is localized at the outer membrane of the mitochondria, our results suggest that this phosphatase may play a pivotal role in coordinating crosstalk between mitochondrial function and cytokine production by NKT cells in diseases such as cancer and acute inflammatory disorders." (PMID 26381214, 2015). "The role of PGAM5 in cancer is not as extensively studied as PGAM1, but it is emerging as an important player in cancer cell biology." (PMID 37847178, 2023).
metabolic disorders (5 papers, 2022 to 2024). "Overall, these data suggested that Pgam5 deficiency alleviates alcohol-mediated hepatic inflammation, lipid peroxidation and metabolic disorder." (PMID 38464835, 2024). "Additional experiments are needed to determine if PGAM5 expression level or phosphatase activity is relevant to PGAM5’s role in tumoral fatty acid metabolism specifically in metabolic disease associated HCC." (PMID 37835490, 2023). "In vivo experiments using hepatocyte-specific Pgam5 knockout (Pgam5hKO) and control mice reveal that Pgam5 deficiency mitigates ethanol-induced liver histopathology, inflammation, lipid peroxidation, and metabolic disorder, further supporting its role in ALD progression." (PMID 38464835, 2024). "Taken together, our present findings and those reported previously by others suggest that PGAM5 is a core regulator in metabolic disease and is a promising candidate target for the design of novel cardioprotective drugs against DCM." (PMID 39285950, 2022).
neurodegenerative disease (5 papers, 2019 to 2025). A disorder of the central nervous system characterized by gradual and progressive loss of neural tissue and neurologic function. "PGAM5 is involved in inflammatory responses, mitosis, apoptosis, lipid metabolism and other processes, and plays an important role in neurodegenerative diseases and ischemia-reperfusion injury." (PMID 39355378, 2024). "In particular, considering the reduction of NFE2L2 or PGAM5 in aging and human degenerative disease states, this NFE2L2-KEAP1-PGAM5 ternary interaction may be an important mechanism in the development of human diseases." (PMID 31057691, 2019).
neurological diseases (5 papers, 2021 to 2025). "In the past decade, many reviews have focused on the biological activities of PGAM5 and the roles of PGAM5 in neurological disorders." (PMID 39930129, 2025). "Previously, we have verified Pgam5 as a mediator in progression of nerve damage by Drp1 phosphorylation-mediated mitochondrial dysfunction, and Pgam5 knockout (KO) alleviated inflammatory responses and neurological disorder in mice with TBI." (PMID 37287985, 2023). "In this review, we discuss the potential role of PGAM5 in mitochondrial homeostasis and neurological diseases." (PMID 34630036, 2021). "This review discusses current knowledge of PGAM5 in neurological diseases and provides future perspectives." (PMID 34630036, 2021). "Nonetheless, exactly how PGAM5 may regulate mitochondrial homeostasis in neurological diseases remains largely unknown." (PMID 34630036, 2021). "However, current studies about neurological diseases only focused full-length PGAM5, while the role of cleaved PGAM5 in neurological diseases remains unknown." (PMID 37221611, 2023). "While regulation of PGAM5-NRF2 mediated mitochondrial biogenesis in neurological diseases had not been previously reported, a recent study revealed that interaction between PGAM5 and NRF2 resulted in blood–brain barrier disruption and neurological deficits in ischemic stroke." (PMID 34630036, 2021).
infection (3 papers, 2020 to 2024). The state of being infected such as from the introduction of a foreign agent such as serum, vaccine, antigenic substance or organism. "Finally, PGAM5 deficient MEFs, upon infection with vesicular stomatitis virus (VSV), revealed diminished IFNβ expression and increased VSV replication." (PMID 32433485, 2020). "ICP34.5 interacts with mitochondrial phosphatase PGAM5 which is responsible for the transport and perinuclear localization of mitochondria under infection-induced stress conditions in neural cells." (PMID 38620036, 2024). "Finally, in order to study whether PGAM5 would have an impact on the replication of VSV, we determined the viral load at 24 h post infection." (PMID 32433485, 2020).
movement disorder (3 papers, 2015 to 2022). Neurological conditions resulting in abnormal voluntary or involuntary movement, which may impact the speed, fluency, quality and ease of movement. "The study on PGAM5-knockout mice showed Parkinson’s-like movement disorders involving dopaminergic neurodegeneration in the SNpc and the abnormal behavioral phenotype was rescued by L-DOPA." (PMID 36389083, 2022). "Mice lacking Pgam5 gene were characterized by a PD like movement disorder, which is thought to be mediated by a dopaminergic neurons degeneration due to an inefficient mitophagy." (PMID 25986246, 2015).
cardiovascular diseases (2 papers, 2022 to 2023). "Prohibitin 2 (PHB2) and phosphoglycerate mutase 5 (Pgam5) have been associated with altered mitochondrial homeostasis in several cardiovascular diseases; however, their role in endotoxemia-related myocardial dysfunction has not been explored." (PMID 37781037, 2023).
PGAM5 also shares sentences with these, for which no sentence is quoted: Parkinson (6 papers); acute kidney injury (2); acute lung injury (2); cardiac diseases (2); melanoma (2); neuroblastoma (2); adenocarcinoma (1); Anxiety (1); autoimmune disease (1); Autoimmunity (1); bacterial infection (1); brain injury (1); cardiomyopathy (1); chronic obstructive pulmonary disease (1); cognitive decline (1); diffuse large B-cell lymphoma (1); experimental autoimmune encephalomyelitis (1); gynecological tumors (1); head and neck squamous cell carcinoma (1); hypertrophy (1); liver (1); male infertility (1); memory impairment (1); Microsporidia Infection (1); non-alcoholic steatohepatitis (1); pancreatic ductal adenocarcinoma (1); pancreatitis (1); pneumonia (1); preeclampsia (1); squamous cell carcinoma (1).